OR3A4P (olfactory receptor family 3 subfamily A member 4 pseudogene)
Description:
Odorant receptor.
Synonyms: formerly OR3A4
Gene: Transcribed unprocessed pseudogene on chromosome 17 (3,310,311 to 3,311,216, forward strand). Ensembl gene ENSG00000180068.
Subcellular location: Cell membrane